ALB (albumin)
Diseases named in the same sentence as ALB in open-access papers (continued):
Sharing a sentence is not in itself a finding about the gene and the disease.
Hypoalbuminemia (continued). "In particular, increased vascular permeability and transcapillary loss of albumin are major causes of acute hypoalbuminemia in systemic inflammatory states, including sepsis and PCAS." (PMID 36579497, 2022). "Combining the diagnostic threshold of hypoalbuminemia and respective average decreased albumin value in the 2 groups, we deduced the recommended preoperative serum albumin value of the patients with STB." (PMID 35571899, 2022). "Patients with malignant tumors often experience hypoalbuminemia caused by the release of a large number of cytokines, including IL-6 released by tumor cells, which can inhibit the synthesis and secretion of albumin by liver cells." (PMID 36313734, 2022). "Our study reveals that preoperative albumin level is an independent risk factor for postoperative hypoalbuminemia, which is more likely to occur when the preoperative albumin value is less than 40 g/L." (PMID 35571899, 2022). "Albumin has strong anti-inflammatory, antioxidant and anticoagulation properties, so hypoalbuminemia can have prothrombotic effects with an increased risk of arterial and venous thrombosis in different clinical settings." (PMID 35223916, 2022). "Albumin is the main zinc binding and buffering protein in serum, and hypoalbuminemia is associated with severe COVID-19." (PMID 35406020, 2022). "Combined with the diagnostic threshold of hypoalbuminemia: 35 g/L, we proposed the preoperative albumin recommended values for two groups of patients: high-risk group: 44 g/L and low-risk group: 40 g/L." (PMID 35571899, 2022). "Due to the nature of the disease and the surgical methods used, patients with STB experience significant decreases in serum albumin and are at high risk of hypoalbuminemia following surgery." (PMID 35187165, 2022). "Our study figured that preoperative albumin was an independent risk factor for postoperative hypoalbuminemia, and the diagnostic threshold value is 40 g/L." (PMID 35571899, 2022). "For low-risk patients and high-risk patients, preoperative albumin values should reach 40 and 44 g/L, respectively, to effectively avoid postoperative hypoalbuminemia." (PMID 35571899, 2022). "In our study we found that complicated pulmonary tuberculosis, preoperative serum albumin value, and operation time are independent risk factors of postoperative hypoalbuminemia." (PMID 35571899, 2022). "In this case, further albumin loss will occur and ultimately result in inhibition of the retrieval pathway and maximal hypoalbuminemia." (PMID 36225307, 2022). "The most common cause of asymptomatic hypocalcemia in animals is hypoalbuminemia because approximately 40% of the total serum calcium is bound to albumin." (PMID 36139324, 2022). "Many studies have shown an increased incidence of hypoalbuminemia in severe COVID-19 patients; in fact, low albumin levels have a strong, positive association with poor disease outcomes." (PMID 36289641, 2022). "For example, hypoalbuminemia is associated with inflammation and synthesis of albumin is suppressed by pro-inflammatory cytokines TNF-α and Interleukin-1, both of which are important mediators of chronic inflammation in PWH." (PMID 36303554, 2022). "Of the 842,672 patients in the ACS-NSQIP cohort, 148,478 (17.6%) had high-risk preoperative serum albumin concentration (≤3.4 g/dL; hereinafter referred to as hypoalbuminemia) and 694,194 (82.4%) had low risk preoperative serum albumin concentration." (PMID 36362771, 2022). "A third inflammation-related mechanism causing hypoalbuminemia is increased hepatic and predominant intracellular degradation, with a consequent reduced albumin half-life leading to a real decrease in body albumin content." (PMID 35740416, 2022). "One of the major disadvantages of the PD, when compared to HD, is protein loss through peritoneal effluent, with an average albumin loss of 4 g per 24 h; therefore, PD patients are at a higher risk for hypoalbuminemia." (PMID 36079811, 2022).
Hypoalbuminemia (continued). "Those who managed to normalize their serum albumin levels and did so early on had consequently a lower risk of complications, even if they initially had postoperative hypoalbuminemia." (PMID 33875388, 2022). "Albumin, a major protein in human serum, reflects the nutritional status of an individual, and hypoalbuminemia has been demonstrated to be associated with poor prognosis in patients with various cancer." (PMID 35549906, 2022). "Recently, multiple studies have suggested a relevant association between perioperative hypoalbuminemia and poor postoperative surgical outcomes and investigated the effect of albumin replacement in these surgical patients." (PMID 35160076, 2022). "Albumin has been used as a nutritional and inflammatory indicator and pre-operative hypoalbuminemia was associated with post-operative complications, mortality, overall survival (OS), and cancer-specific survival (CSS)." (PMID 36105581, 2022). "Studies have suggested that hypoalbuminemia in hypertensive patients likely occurs due to endothelial dysfunction, capillary leakage, as well as albumin loss in renal tubules, which are directly related to blood pressure levels." (PMID 36386913, 2022). "Logistic regression analysis showed that operation time, preoperative albumin and peroperative globulin were independent risk factors of postoperative hypoalbuminemia in brain tumor postoperative patients." (PMID 34996896, 2022). "The general PPK model showed significant associations of patients with hypoalbuminaemia (ALB <35 g/L) with increases in both CL and V (ΔOFV = 77.9), which means the degree of hypoalbumenia had impact on caspofungin pharmacokinetics." (PMID 36408257, 2022). "Some studies have shown that postoperative albumin loss is positively correlated with preoperative albumin level, which is considered to be a protective factor for postoperative hypoalbuminemia, which is consistent with our research’s results." (PMID 35571899, 2022). "In univariate analysis, BMI, intraoperative blood loss, intraoperative total input, intraoperative total urine output, operation time, red blood cells, PT, albumin, globulin and A/G ratio were significantly associated with postoperative hypoalbuminemia." (PMID 34996896, 2022). "Patients with hypoalbuminemia significantly predicted the risk of stroke with an odds ratio of 0.08 [95% confidence interval (CI), 0.01–0.68, p = 0.020] per 1 g/day of serum albumin in the filter group." (PMID 36186979, 2022). "Successively, lower plasma P-SH levels in CKD patients were correlated to lower plasma albumin levels (hypoalbuminaemia), suggesting a causal relationship between hypoalbuminaemia and lower plasma P-SH levels." (PMID 35269995, 2022). "Patients with hypoalbuminemia had a significantly (p = 0.020) higher risk of stroke within 6 months, and the odds ratio was 0.08 (95% CI: 0.01–0.68) per 1 g/dl of serum albumin." (PMID 36186979, 2022). "Albumin-free zinc is excreted from the urine in a hypoalbuminemic state, and the loss of zinc from the body due to hypoalbuminemia is considered the main pathogenesis of zinc deficiency resulting from advanced liver disease." (PMID 36432541, 2022). "A cut-off level of serum albumin <30 g/L has been identified in the association of hypoalbuminemia and increased ICU and hospital mortalities of ICU patients." (PMID 36430652, 2022). "The application of serum albumin level as a diagnostic or prognostic factor, outside the setting of hypoalbuminemia-associated disorders (HAD) has gained only little attention." (PMID 35268297, 2022). "Of note, serum albumin is negatively correlated with D-dimer and CRP, and hypoalbuminemia is linked with the development of coagulopathy in COVID-19 patients through a decrease in the anticoagulant and antiplatelet effects of albumin." (PMID 35783600, 2022).
Hypoalbuminemia (continued). "These factors included alteration of consciousness at first presentation, having a malignancy as an underlying disease, hypoalbuminemia (albumin ≤2.5 mg/dL) at first presentation, and having a concurrent respiratory infection." (PMID 35740233, 2022). "Third, all three NSTs include serum albumin as a parameter, while hypoalbuminemia was confirmed to be associated with extremely poor prognosis and cardiac cachexia." (PMID 35284455, 2022). "Low haemoglobin and albumin levels have been identified as strong predictors of TB mortality and in China and Israel, an association between hypoalbuminaemia and poor prognosis in DR-TB patients has been reported." (PMID 36490236, 2022). "ALB is reduced in acute inflammation, and hypoalbuminemia is associated with systemic inflammatory responses." (PMID 36284270, 2022). "ACAG, which is combined serum albumin and AG, can be used to distinguish acidosis caused by acid load or base deficit, which correspond to two pathological states of human body-hypoalbuminemia and metabolic acidosis." (PMID 36112320, 2022). "For all evaluated dosing regimens, patients with hypoalbuminemia (ALB < 3.5 g/dL) were at greater risk of toxicity, especially when combined with impaired renal function." (PMID 33672057, 2021). "Two other associated factors for vitamin D deficiency in this study were low albumin level (hypoalbuminemia) and high SOFA score." (PMID 34966771, 2021). "Our study found that hypokalemia in patients with anorexia nervosa during refeeding is associated with a lower body mass index and hypoalbuminemia (low levels of serum albumin), in addition to binge–purge behavior." (PMID 34362446, 2021). "As pre-operative hypoalbuminemia is considered a risk factor for wound complications, our final logistic regression model identified lower serum albumin and higher CIT as significant determinants only for the development of a hematoma." (PMID 34322515, 2021). "In this study, severe pre-RTx hypoalbuminemia was associated with an increase incidence of post RTx CMVd and the dose–response relationship showed a slight decrease in CMVd risk with higher albumin levels." (PMID 33919676, 2021). "Previous studies have shown that hypoalbuminemia (low serum albumin concentration) is associated with overhydration in patients undergoing maintenance dialysis." (PMID 33891656, 2021). "In the present study, hypoalbuminemia (serum albumin less than 3.5 g/dL) was detected as a risk factor for anti-TB-induced hepatotoxicity, which is supported by some other reports." (PMID 34903999, 2021). "Serum albumin plays an important role in proximal tubular homeostasis, and hypoalbuminemia has been reported as a strong risk factor for postoperative AKI in both cardiac and non-cardiac surgery." (PMID 34064893, 2021). "A large observational study (n = 2818) found that 94% of patients with normal preoperative serum albumin levels developed hypoalbuminaemia at 24 h after cardiac surgery, where the risk of AKI approximately doubled with each 5 g/l reduction." (PMID 34419128, 2021). "Hypoalbuminemia is associated with the acquisition and severity of infectious diseases, and intact innate and adaptive immune responses depend on albumin." (PMID 33925831, 2021). "So, the aim of this study is to investigate the risk factors of perioperative hypoalbuminemia in hip arthroplasty and the relationship between preoperative albumin level and postoperative complications in the elderly." (PMID 34526075, 2021). "Increased albumin concentration instrumented by 2 hypoalbuminemia-associated SNPs (rs2894536 and rs10972486) was associated with decreased HRs for hypertension development (HR = 0.762, 95% CI 0.659–0.882 and HR = 0.759, 95% CI 0.656–0.878)." (PMID 34050200, 2021).
Hypoalbuminemia (continued). "Albumin is considered the main modulator of fluid distribution and main generator of oncotic pressure since acquired hypoalbuminemia is associated with arterial hypotension all the way to circulatory shock, intravascular volume depletion and pitting edema." (PMID 33941197, 2021). "Albumin serum level and blood volume decrease continuously with increased age and hypoalbuminemia becomes a natural, additional risk of death for aged persons." (PMID 34281177, 2021). "The decreased ALB content was probably due to inflammatory process caused by Salmonella infection, and it was previously reported that ALB reduction (hypoalbuminemia) can be caused by GIT diseases." (PMID 33535430, 2021). "The occurrence of VTE increases at serum/plasma albumin levels <20–25g/L and therefore hypoalbuminemia is considered a risk factor (or marker for risk factor) for VTE in NS." (PMID 34319998, 2021). "The kinetics of albumin involve trans-capillary leak and breakdown, leading to hypoalbuminemia, which is associated with worse outcomes in a broad spectrum of conditions." (PMID 33925831, 2021). "Increased age and hypoalbuminemia (serum albumin < 3.7 g/dL versus ≧ 3.7 g/dL) were two significant risk factors for the development of first episode of peritonitis in the multivariable model, but low serum PTH alone was not a risk factor." (PMID 33441921, 2021). "It was suggested that the mechanism underlying hypoalbuminemia in COVID-19 patients is albumin excretion into damaged organs." (PMID 34736472, 2021). "Despite the association between hypoalbuminemia and adverse outcomes of various critical illnesses, data on the prognostic value of albumin levels for outcomes among IHCA patients (particularly those measured before cardiac arrest) are limited." (PMID 34017041, 2021). "This retrospective medical records study showed that duration of severe hypoalbuminemia (S/P-albumin <20g/L) in NS is a risk factor for both VTE and bleeding." (PMID 34319998, 2021). "Hypoalbuminemia and other indices reflecting low serum albumin levels were associated with reduced survival, increased treatment-related toxicity, and a low treatment response rate." (PMID 34001060, 2021). "At the same time, the cause of postoperative hypoalbuminemia is not only blood loss during the perioperative period, but is also related to abnormal vascular permeability and albumin metabolism." (PMID 34526075, 2021). "Increased permeability of vessels due to inflammation causes albumin to escape into the pleural cavity, resulting in hypoalbuminemia." (PMID 34438744, 2021). "Hypoalbuminemia as an associated factor for vitamin D deficiency was revealed in a previous study, and their multivariable analysis revealed that serum albumin level was associated with vitamin D deficiency with an OR of 0.92 (95% CI 0.87-0.97)." (PMID 34966771, 2021). "Fourth, calcium homeostasis is difficult to assess, and even if the measurement is corrected for albumin in patients with hypoalbuminemia, there is a risk of obtaining incorrect results." (PMID 34684395, 2021). "Hypoalbuminemia can be caused by poor food intake/absorption, older age, the presence of comorbidities, and proinflammatory cytokines that inhibit albumin production." (PMID 33450916, 2021). "We report a significant increase in risk of mortality among older adults with severe hypoalbuminemia defined as serum albumin level less than ≤3 g/dL at the time of admission for a SARS-CoV-2 infection." (PMID 34768653, 2021). "Albumin serves as a biochemical marker of nutritional status, and hypoalbuminemia is associated with poor functional outcome." (PMID 35011900, 2021). "Duration of severe hypoalbuminemia (S/P-albumin <20g/L) in NS is a risk factor for both VTE and bleeding." (PMID 34319998, 2021). "Hypoalbuminemia, a condition caused by albumin leakage outside the blood vessels following high vascular permeability, is a characteristic feature of KD." (PMID 34434074, 2021).
Hypoalbuminemia (continued). "Intravenous administration of albumin preparations in the state of hypoalbuminemia causes a rapid, temporary correction of the oncotic pressure and prevents hypovolemia." (PMID 34071680, 2021). "We aimed to evaluate hypoalbuminemia as a risk factor and the prognostic value of human serum albumin in AP." (PMID 34921151, 2021). "Hypoalbuminemia can occur due to different causes such as decreased production, increased loss, increased use in the body, or abnormal distribution of albumin between the body parts." (PMID 34007754, 2021). "The present study shows that duration of severe hypoalbuminemia, S/P-albumin <20g/L, is a strong risk factor for developing venous thromboembolism for NS patients, increasing the risk of thrombosis more than 20-fold." (PMID 34319998, 2021). "Albumin has multiple biological characteristics, and hypoalbuminemia is a risk factor of mortality in certain diseases." (PMID 34221734, 2021). "Albumin comprises about 55% of the total serum protein, and cancer-associated hypoalbuminemia is associated with a variety of systemic changes in response to the tumor." (PMID 34884980, 2021). "In clinical practices, hypoalbuminemia is meant by the concentration of serum albumin lower than 35 g/L, and is mainly associated with malnutrition." (PMID 34445989, 2021). "A meta-analysis of seven large-scale articles detailing the complications of albumin led to an all-cause relative risk increase of 1.93 when operating with hypoalbuminemia." (PMID 33939393, 2020). "But presently, there is a paucity of data on the association between hypoalbuminemia, reversal of albumin-to-globulin ratio and morbidity outcome in LF infection." (PMID 33312698, 2020). "Patients with liver damage almost always have hypoalbuminemia caused by decreased albumin synthesis by the hepatocytes." (PMID 31832977, 2020). "In NS, generally, loss of urinary albumin cannot be compensated by increased albumin synthesis in the liver, and thus, hypoalbuminemia and hypoproteinemia are observed." (PMID 32686569, 2020). "Hypoalbuminemia is a condition associated with a deficiency in albumin caused by a reduction in protein intake, and its prevalence is related to patient age and gender, comorbidities, and dietary intake." (PMID 32518615, 2020). "Compared with patients with normal albumin concentrations, patients with hypoalbuminemia had a higher risk of surgical site infection, pneumonia, prolonged hospital stay, and readmission." (PMID 33203417, 2020). "Carnitine deficiency impairs the important metabolic processes of the liver, such as gluconeogenesis, fatty acid metabolism, albumin biosynthesis, and ammonia detoxification by the urea cycle, and causes hypoalbuminemia and hyperammonemia." (PMID 32610446, 2020). "Meta-analysis of seven large-scale studies detailing the complications of albumin led to an all-cause RR increase of 1.93 when operating with hypoalbuminemia." (PMID 33939393, 2020). "The factors leading to hypoalbuminemia are often complicated and associated with operative case type, ALB loss, redistribution, catabolism, or theirs combination." (PMID 33585551, 2020). "Generally, hypoalbuminemia is commonly recognized in elderly populations caused by poor dietary intake, protein loss, or catabolic metabolism; therefore, albumin can reflect the inflammation and immune status of cancer cells." (PMID 32595832, 2020). "The cut-off level of albumin (< 2.8 g/dL) in our prediction model is consistent with that used in previous studies, which showed that hypoalbuminemia, defined as < 2.7 or < 2.9 g/dL, was an independent risk factor for mortality in patients with sepsis." (PMID 33308206, 2020). "Serum lower zinc concentration was associated with hypoalbuminemia, suggesting that we should be careful to evaluate zinc deficiency when albumin level is low." (PMID 32102170, 2020). "In the studies isolating only albumin, hypoalbuminemia is associated with increased risk for postoperative complications." (PMID 33939393, 2020).